CFAP91 (cilia and flagella associated protein 91)
Description:
Involved in sperm flagellum axonemal organization and function. May regulate cilium motility through its role in the assembly of the axonemal radial spokes (By similarity).
Synonyms: AAT-1; AAT1; C3orf15; MAATS1; AAT1alpha; SPATA26; CaM-IP2; SPGF51
Tractability: Small molecule: a structure with a bound ligand is known. PROTAC: ubiquitination databases record sites on it.
Gene: Protein-coding gene on chromosome 3 (119,703,022 to 119,767,102, forward strand). Ensembl gene ENSG00000183833.
Subcellular location: Mitochondrion; Cytoplasm; Cytoplasm, cytoskeleton, cilium axoneme; Cytoplasm (Isoform 7)
Gene Ontology:
Molecular function: protein binding
Biological process: axonemal central apparatus assembly; spermatogenesis; cilium movement
Cellular component: cytoplasm; mitochondrion; axoneme; motile cilium; radial spoke stalk
Genetic constraint (gnomAD): Loss-of-function variants: 62 observed, 67.83 expected, observed/expected ratio (o/e) 0.91, 90% interval 0.74 to 1.13. The upper end of that interval is the gene's LOEUF score, 1.13, which puts it in group 4 of 6, group 1 being the genes least tolerant of losing a copy. Missense variants: 719 observed, 728.57 expected, observed/expected ratio (o/e) 0.99, 90% interval 0.93 to 1.05. Synonymous variants: 247 observed, 258.73 expected, observed/expected ratio (o/e) 0.95, 90% interval 0.86 to 1.06.
Homologues: Orthologues: chimpanzee CFAP91 (99% identical), macaque CFAP91 (97% identical), dog CFAP91 (83% identical), pig CFAP91 (82% identical), mouse Cfap91 (75% identical), rat Cfap91 (74% identical), rabbit CFAP91 (71% identical), guinea pig CFAP91 (64% identical), tropical clawed frog cfap91 (58% identical), zebrafish cfap91 (52% identical), Drosophila melanogaster CG15144 (17% identical), Drosophila melanogaster CG15143 (15% identical), and 1 more.
Diseases named in the same sentence as CFAP91 in open-access papers:
CFAP91 is named in the same sentence as 11 diseases in open-access papers, as found by Europe PMC text mining. Sharing a sentence is not in itself a finding about the gene and the disease. The quoted sentences say what the papers report.
male infertility (3 papers, 2024 to 2025). The inability of the male to effect fertilization of an ovum after a specified period of unprotected intercourse. "By using proximity labeling, this study uncovers EFCAB5 as a sperm-specific protein associated with CFAP91 in sperm tails, revealing its crucial role in regulating sperm motility and offering insights into the molecular basis of male infertility." (PMID 40931011, 2025). "CFAP91, an RS3 protein, is implicated in human male infertility, yet its molecular function remains poorly understood." (PMID 40931011, 2025). "Here, we demonstrate that Cfap91 knockout (KO) mice exhibit impaired sperm flagellum formation and male infertility." (PMID 40931011, 2025). "Damaging mutations in genes encoding RS1 and RS2 components cause PCD, while mutations in genes encoding RS3 proteins, CFAP61, CFAP91, CFAP251, and LRRC23 result in male infertility but not PCD." (PMID 40886204, 2025). "Our findings establish CFAP91 as an essential scaffolder of RS3 assembly and EFCAB5 as a sperm-specialized movement regulator, advancing understanding of axonemal specialization in mammalian spermatozoa and its relevance to male infertility." (PMID 40931011, 2025). "Strikingly, in mice and humans, mutations in CFAP61, CFAP91, CFAP251, and LRRC23 cause male infertility but not primary ciliary dyskinesia or hydrocephalus, suggesting more differences in the RS3 structure and/or function between sperm flagellum and cilia in multiciliated cells." (PMID 40886204, 2025).
Hydrocephalus (1 paper, 2025). Hydrocephalus is an active distension of the ventricular system of the brain resulting from inadequate passage of CSF from its point of production within the cerebral ventricles to its point of absorption into the systemic circulation. "As mutations in other Cfap genes were reported to cause hydrocephalus, we hypothesized that Cfap91-/- mice in the B6D2 background may also carry hydrocephalus." (PMID 40931011, 2025).
Infertility (1 paper, 2025). "To test the fertility, we caged Cfap91-/- males with WT females and found that Cfap91-/- males were infertile in 3 trials." (PMID 40931011, 2025). "To discover why Cfap91-/- males were infertile, we first performed a gross inspection of their testes." (PMID 40931011, 2025). "To confirm whether the infertility found in Cfap91-/- males was caused by the absence of Cfap91 but not by other factors, we generated Cfap91 TG mice." (PMID 40931011, 2025).
teratozoospermia (1 paper, 2025). "Overall, our results indicate that spermiogenesis was abnormal in Cfap91-/- males, which resulted in oligo-astheno-teratozoospermia." (PMID 40931011, 2025).
tumor (2 papers, 2016 to 2023). "To further study the role of differentially expressed lncRNAs in tumor, we discovered through GO enrichment analysis that most differentially expressed lncRNAs were related to microtubule movement, including DYNLRB2, CFAP91, and ZMYND10." (PMID 37224123, 2023).
CFAP91 also shares sentences with these, for which no sentence is quoted: angiomyolipoma (1 paper); cancer (1); diabetes (1); hyperlipidemia (1); Hypertension (1); metabolic disease (1).